CD44 (CD44 molecule (IN blood group))
Diseases named in the same sentence as CD44 in open-access papers (continued):
Sharing a sentence is not in itself a finding about the gene and the disease.
tumor (continued). "Furthermore, clarification of the composition and role of the EMP3:CD44 complex in other cells and tissues offers an approach to understanding and manipulating the tumour suppressor and oncogenic properties of EMP3 in diverse cancers." (PMID 32678083, 2020). "Effects of CD44 cross-linking on tumor metastasis were evaluated by Transwell assay." (PMID 33292278, 2020). "Additionally, when studying the distribution and binding of phage particles to a tumor xenograft, we must take into account the fact that the number of CD44+/CD133+ cells inside xenograft is small." (PMID 33396774, 2020). "As reported, CD44 in the basal layer oftumor cellular epidermis could be specifically recognized by HA, indicating that the over-expressed CD44 on thesurface of tumor cells could be used as a specific receptor for targeted drug delivery." (PMID 31924103, 2020). "As numbers of CD25+CD44+c-kit+ DN2 cells increase in tumor-bearing mice, we evaluated whether tumor progression led to enhanced DN2-cell proliferation." (PMID 32582141, 2020). "CD44 is a stemness markerinvolved in cell adhesion and tumor metastasis." (PMID 32779438, 2020). "Furthermore, inhibition of PLK1 blocked the growth of CD44 high/CD24-/low tumour-initiating cells in TNBC." (PMID 32050983, 2020). "In fact, cancer-specific glycosylation may add another layer of tumor specificity to proteins such as CD44." (PMID 31973075, 2020). "Similarly, Gao and co-workers reported the CD44-mediated uptake of the PS chlorin e6 loaded in HA nanocomplexes in CD44+ HT-29 cells in vitro and in HT-29 tumor bearing mice." (PMID 31979218, 2020). "Our results and the evidence demonstrating that cell-ECM interactions boost tumor cells’ stemness led us to hypothesize that the enhancement of CSCs population may be due to HA through increases of CD44 expression." (PMID 33375053, 2020). "Interaction between hyaluronan and CD44 in cancer decreases endothelial cell-cell contacts, leading to endothelial cells barrier disruption, which is an initial event of aberrant angiogenesis in tumor." (PMID 33312163, 2020). "CD44 is the first discovered and the most commonly used surface marker of BCSCs, which plays an important role in all aspects of tumor cells, such as growth and proliferation, migration, differentiation, apoptosis, self-renewal, microenvironment, EMT, and drug resistance." (PMID 33584277, 2020). "Activation of IFN-ß signaling pathways in non-CSCs blocks the expression of CD44 and Snail, which causes a decrease tumor sphere formation and additionally inhibits invasion." (PMID 32849491, 2020). "In HCC, CD44 is TIC marker most associated with the epithelial-mesenchymal transition (EMT), drug resistance and tumor formation in immunodeficient mice, suggesting that CD44 expression might be a crucial sign to guide clinical treatment." (PMID 31992334, 2020). "Moreover, the percentage of CD44‐positive cells was dramatically increased in the tumor‐relapse samples compared with the tumor samples from the first surgery." (PMID 31746135, 2020). "Statistical analysis showed that CD44+/CD133+ HuGSCs accounted for 1% of all tumour cells." (PMID 32174801, 2020). "Also, the numbers of CD44/CD41/61-positive aggregates steadily increased over the course of tumor progression: significant changes were observed between subsequent time points, apart from between the second and the third weeks." (PMID 32191918, 2020). "The role of CD44 in tumorigenesis is related to its connection with extracellular matrix components such as hyaluronic acid, osteopontin and growth factors present in the tumor microenvironment." (PMID 33303880, 2020). "In addition, TQ significantly decreased the T47D associated stem cell clone (CD44+/CD24) by 19.9 ± 0.8%, while PTX caused a 9.9 ± 0.2% decrease in the tumor-associated stem cell clone." (PMID 31968657, 2020). "Furthermore, the third-generation tumor xenografts derived from HCT116 or HT29-CD133+CD44+ cells presented the same histopathological features." (PMID 32729895, 2020).
tumor (continued). "Importantly, they discovered that GSCs with greater expression of CD44 in the tumor margin in comparison with the center correlates with highly invasive feature, shorter survival, and faster tumor progression." (PMID 32429463, 2020). "Furthermore, we intended to reduce the amount of soluble CD44 in the sample, which is shed by matrix-metalloproteases from the surface of tumor and non-tumor cells." (PMID 33003586, 2020). "Furthermore, the transfer of CD44/CD44v6 expressed by EVs supports tumor initiation and progression." (PMID 33050539, 2020). "We also investigated the interaction between TAMs and GCSC markers and delineated the molecular mechanism of CD44 induction that allowed infiltrated macrophages in the tumor microenvironment to contribute to redox adaptation through CD44 upregulation by miR-328 suppression." (PMID 31935894, 2020). "Consequently, when we inhibited CD44 expression on TMPs by a pharmacological or a genetic approach, increased tumor cell adhesion and re-organized actin filament structure were observed." (PMID 33050539, 2020). "However, 1 × 104 CD133+CD44+ cells not only initiated tumor growth in the colorectum but also robustly generated metastatic lesions in the gut and liver after 14–18 weeks." (PMID 32729895, 2020). "Cross-linking of CD44 on tumor cells was reported to induce LFA-1 and VLA-4 expression." (PMID 32092981, 2020). "In vitro experiments showed that, inhibition of the CD44-MMP axis may provide therapeutic targets for reducing the tumour spread which further establishes a positive association between MMP9 and CD44 expression." (PMID 32445177, 2020). "Alternatively, CD44 targeting may serve to specifically deliver cytotoxic drugs or radioisotopes to tumor cells." (PMID 32793493, 2020). "CD44-targeted NIR-PIT combined with CTLA4 blockade showed more effective tumor killing and complete remission in MOC1 tumors than NIR-PIT combined with PD-1 blockade in a previous study whereas in MC38-luc and LL/2 tumors NIR-PIT combined with PD-1 blockade was more effective." (PMID 32937841, 2020). "While time to tumor endpoint (2 cm3) was unaffected by CD44 KO in vivo, we found that Hs578T cells took a significantly longer amount of time to form palpable tumors, consistent with delayed onset noted in the overall survival based on tumor burden." (PMID 32455980, 2020). "Moreover, iRGD-Exos loaded with siRNA/CD44 inhibited the cell proliferation in vitro and tumor growth in vivo." (PMID 32760666, 2020). "If tumor cells possess receptors (CD44, P-selectin, integrins..)." (PMID 32575608, 2020). "Several studies indicate AMPK signaling participates in the formation of CD44-positive CSC, and targeting CD44 could result in tumor inhibition by inducing AMPK activation." (PMID 33168816, 2020). "Furthermore, extracellular and cell surface proteoglycans with their interaction with cell surface proteins such as CD44 have been known to promote tumor cell growth and migration." (PMID 32665557, 2020). "Second, CD44 is also expressed on activated immune cells within the tumor treatment field, raising the concern that CD44-targeted NIR-PIT could also eliminate some proportion of desirable effector immune cells." (PMID 32937841, 2020). "For example, PRG4 may contribute to restrain antitumor CD4+ or CD8+ T lymphocytes within the tumor by binding to CD44 expressed on these cells." (PMID 33199679, 2020). "Additionally, high expression of CD44 correlates with epithelial-to-mesenchymal transition and with stem cell-like properties, contributing to tumor invasion, metastasis, disease recurrence and chemoresistance." (PMID 32257947, 2020). "Similarly, CD44-expressing EVs also contribute to metastasis by remodeling the ECM within the primary tumor, supporting tumor cell invasion." (PMID 33050539, 2020). "The 89Zr-labeled humanized mAb, RG7356, also showed specific tumor uptake in CD44+ tumors." (PMID 32560337, 2020).
tumor (continued). "We hypothesized that CD44 induces the radioresistance of GBM due to the increased existence of CSCs in better tumor coverage of the irradiated brain region." (PMID 31746135, 2020). "Multivariate survival analysis showed that CD44 expression was not linked to tumor-specific survival, overall survival, and recurrence/relapse-free survival, but was associated with disease failure (HR = 2.912, 95% CI = 1.51–5.61)." (PMID 32434417, 2020). "Consequently, CD44 demarks stem cells in normal tissues and tumor-initiating cells isolated from neoplastic tissues." (PMID 32231069, 2020). "Based on sensitivity analyses, the re-calculated pooled results showed a negative correlation between CD44 expression and advanced tumor grade and a positive association between CD44 expression and advanced T stage." (PMID 32434417, 2020). "Serglycin, the only intracellular PG, promoted tumor cell growth through interacting with CD44, and it was found that combining targeting serglycin and CD44 could be an effective therapy." (PMID 32825245, 2020). "However, in non-tumor tissues, the disease-free survival rate in the CD44-low expression group was significantly longer, compared to the CD44-high expression group." (PMID 32466488, 2020). "Moreover, CD44 is a cancer stem cell marker and mediates signaling pathways for tumor differentiation, invasion, and metastasis." (PMID 32471201, 2020). "Genes regulated by CD44-ICD as a transcriptional or co-transcriptional factor could regulate tumor progression." (PMID 33062960, 2020). "Importantly, this study also observed increased CD44 expression in CTCs compared to patient-matched primary tumor biopsies, again highlighting a potential role of CD44 in CTC analysis." (PMID 32984308, 2020). "Importantly, tumor-infiltrating macrophages, often prominent in the tumor environment, also expressed CD44 and ALDH1." (PMID 32532153, 2020). "Moreover, EMT activation via the Ras-MAPK signalingpathway in normal breast CD44-/CD24+ cells leads to their transformation intoCD44+/CD24- stem tumor cells; additional activation of TGF-β1 enhances theeffect." (PMID 33173593, 2020). "It has been shown that ESRP1/2 activation leads to oncogenic activation of several ESRP1/2 target genes such as MAP 3 K7, mTOR, GSK3ß, RB1, CTNND1, E-Cadherin, and CD44, which drive tumor cell proliferation and EMT, key features of advanced and aggressive cancers." (PMID 33339518, 2020). "Interestingly, common interactions were observed between myeloid cells and epithelial cells, with the most frequent ligand-receptor pair HBEGF_CD44, of which dysregulations were involved in tumor and metastasis initiation." (PMID 33287869, 2020). "CD44 can be a target for HA-coated anti-tumor liposomes towards CSCs." (PMID 33303029, 2020). "HA-coated nanoparticles containing anti-tumor drugs could also target CD44-positive cancer cells with high specialization and efficient drug delivery, refining the current anti-cancer management." (PMID 33303029, 2020). "Our findings indicate that combinatorial treatment of ATRA with gefitinib could reduce CSC-mediated resistance by down-regulating expression of ALDH1A1 and CD44 and potentiate the anti-tumor effect of gefitinib in NSCLC/ADC." (PMID 32293355, 2020). "It is known that elevated levels of soluble CD44 in the serum of patients is a marker of tumor burden and metastasis in several cancers, hence, the glycans on soluble CD44 may provide more information regarding to disease status." (PMID 32102970, 2020). "Accordingly, CD44, which has been consistently reported on CTCs in most types of cancer, was recently shown to contribute to intravascular aggregation of tumor cells through the formation of homophilic intercellular interactions." (PMID 32575608, 2020). "Only weak CD44 expression was seen in 3/30 (10%) of the tumours." (PMID 32245446, 2020).
tumor (continued). "In addition, CAFs promote tumor forming ability and stemness when co-implanted with PCa cells in mice xenografts, and importantly, these tumor-repopulating cells were found to be CD44-positive and CD24-negative." (PMID 32754615, 2020). "The expression of CD133 and CD44 on the cell surface is considered a marker of stemness in several cancer types, including prostate, as these proteins are involved in cell–cell interactions, cell adhesion and migration of tumor cells." (PMID 32811873, 2020). "In particular, BCa cell lines were cultured alone (BCa only), in combination with a healthy microenvironment (HME) derived from healthy breast tissue, or in combination with a tumor microenvironment (TME) containing accessory cells derived from BCa tumor biopsies after sorting out CD44+ BCa cells." (PMID 32610529, 2020). "It has been shown that high ABCB5 expression was significantly related to tumor formation, metastasis and recurrence in OSCC and ABCB5 was co-labeled with CD44 (oral CSC marker), suggesting ABCB5 was associated with oral CSCs and multistep carcinogenesis of OSCC." (PMID 32357409, 2020). "CD44 expression using IHC method was not linked to tumor grade and T stage, but was closely associated with lymph node metastasis." (PMID 32434417, 2020). "CD44 is reported to be involved in tumor invasion and metastasis." (PMID 32434417, 2020). "CD44 proteins comprise a major class of single-pass transmembrane glycoproteins and connect the extracellular matrix to the cytoskeleton to induce downstream signaling for the promotion of tumor invasion." (PMID 32943996, 2020). "The alternation of the tumor immunological environment also influences the expression of CD44." (PMID 33381460, 2020). "Soluble biglycan can interact with different combinations of multiple surface receptors, including toll-like receptors (TLRs) 2 and 4, CD14 and CD44, that in turn influence processes such as autophagy, angiogenesis, cell growth and migration, to finally promote tumor progression or suppression." (PMID 33199679, 2020). "Moreover, the expression of CD44 isoforms is reportedly highly correlated with the production of various tumor subtypes and has been used as a marker for cancer stem cells in many cancers." (PMID 32344833, 2020). "Moreover, the tumorigenic stem-like cell marker CD44 expression was analysed in tumour sections by immunofluorescence assay." (PMID 31388092, 2019). "Many cancer cells, including tumor-initiating stem cells, are known to overexpress the HA-binding receptor CD44, and HA has often been modified with a drug carrier in attempts to improve drug delivery to CD44-overexpressing cancer cells." (PMID 31097014, 2019). "A small population of cells that were CD44+/CD24- formed tumor spheres." (PMID 31612865, 2019). "The increased expression of both PD-1 and CD44 suggests that the tumors from mice treated with radiation and anti-PD-L1 are experiencing increased rates of tumor antigen presentation, which could be one mechanism for decreased tumor growth in the treated mice." (PMID 31412954, 2019). "However, few cases showed enrichment of CD133 and CD44 expression in distal margin tissues as well and CD44 showed a significantly enriched expression in tumours (Log2FC of 1.09, P = 0.0044)." (PMID 30950180, 2019). "A vitamin D derivative could inhibit the tumor growth and the expression of cancer stem cell marker CD44 in human breast cancer." (PMID 30631035, 2019). "Furthermore CD44 is involved in formation of tumor leading front by binding the matrix metalloproteinase (MMP) MMP9." (PMID 31803736, 2019). "Overexpression of CD44 is supposed to be related to higher aggressiveness of the tumor." (PMID 31810195, 2019). "Furthermore, we elucidate additional targets of FKBPL such as DLL4 and Notch 4, which in addition to CD44, are potentially involved in the multiple anti-tumour effects of FKBPL and its therapeutic peptide derivatives." (PMID 30975104, 2019).
tumor (continued). "Furthermore, curcumin loaded CD44+ targeting nanomicelles resulted in the potent suppression of pro-tumour NF-κB signalling." (PMID 31835751, 2019). "We found that depletion of SHCBP1 remarkably repressed the cellular stemness enhancement caused by EGF stimulation, as revealed by reduced EGF-promoted formation of tumor spheres, expression of stem cell markers, and CD44/EpCAM double-positive as well as SP fraction." (PMID 30177836, 2019). "Furthermore, when MDA-MB-468 shCD44 + 3T3HAS3 CD44 KO T1 tumors were co-grafted into CD44 KO nude mice, tumor growth was increased when CD44 expression was lost or diminished." (PMID 31762938, 2019). "Indeed, studies show a strong correlation between high CD44 expression levels and tumor metastasis, invasion, and prognosis." (PMID 31294922, 2019). "A variety of unique CD44 isoforms have been detected in cancer cells and tumor samples." (PMID 31293964, 2019). "CD44 is a membrane glycoprotein that induces signal transduction among cells, and its expression is correlated with migration, metastasis, and poor prognosis in several tumours." (PMID 31139014, 2019). "By binding with CD44, HA induces conformational changes leading to adaptor protein recruitment to the intracellular cytoplasmic tail of CD44 and the subsequent activation of various signaling pathways involved in tumor progression." (PMID 31608236, 2019). "Using this model, the dependence of tumor growth on HA and CD44 was investigated." (PMID 31762938, 2019). "However, the functions of CD44 are controversial since it seems to act both as a suppressor and a promoter of tumor progression, depending on the tumor cell type and the experimental setup." (PMID 30909497, 2019). "Furthermore, CD44 has been suggested as a diagnostic marker for CSC and as a prognostic marker for different tumor entities correlating with a poor prognosis of tumor patients." (PMID 31741714, 2019). "Furthermore, CD44+/CD24− was found to be present in 50% of pretreatment tumor biopsies of patients with residual EAC after treatment in surgical specimens but absent in all biopsies of patients who had a pathological complete response after nCRT." (PMID 31200527, 2019). "Interestingly, CD44 staining of CD44-expressing tumors revealed a high number of EVs of different size in the stromal areas (arrows), while the tumor cells as well as the stroma of MOCK tumors were completely negative for CD44 immunostaining." (PMID 30909497, 2019). "Moreover, in an experimental lung metastasis model (tail vein injection of tumor cells in vivo), the rate of metastatic nodules in the lungs was significantly higher in mice with CD44+ cells than CD44− cells." (PMID 31315262, 2019). "Studies have found that CD44 as a kind of transmembrane glycoprotein was the surface receptor of hyaluronidase, it participated in the regulation of intracellular environment and had functions of promoting tumor growth, invasion and metastasis, and CD44v6 was one of the major variations of CD44." (PMID 31086549, 2019). "As a cell-surface marker for malignant tumors, CD44 indicates tumor cell invasion and metastasis." (PMID 31569420, 2019). "In view of BC-related function of these BLBC-specifically secreted proteins, several factors involved in tumor progression and metastasis showed increased secretion, including CD44, heat shock protein family A member 5 (HSPA5), and heat shock protein 90 beta family member 1 (HSP90B1)." (PMID 31146747, 2019). "Additionally, this upregulation of CD44 and CTTN activated the Wnt pathway and further upregulated the expression of CD44, which is a widely accepted marker in stem tumor cells." (PMID 30832692, 2019). "Furthermore, compared to SMA nanogels, HA-SMA nanogels exhibited a marked increase in the anticancer activity towards in CD44+ tumor cells." (PMID 31311150, 2019).